NF1 (neurofibromin 1)
Diseases named in the same sentence as NF1 in open-access papers (continued):
Sharing a sentence is not in itself a finding about the gene and the disease.
tumor predisposition syndrome (35 papers, 2012 to 2025). "Neurofibromatosis type 1 (NF1) is a tumor predisposition syndrome caused by alterations in NF1 gene that lead to tumor growth throughout the nervous system, which can cause morbidity and mortality, and transform to malignancy." (PMID 41022755, 2025). "NF1 is one of the most common tumor predisposition syndromes and is caused by the loss of function of the NF1 tumor suppressor gene." (PMID 39857962, 2025). "Germline mutations in NF1 cause neurofibromatosis type 1 (NF-1), a tumor predisposition syndrome associated with benign and malignant tumors primarily in the peripheral and central nervous system." (PMID 39472976, 2024). "The role of NF1 has been commonly studied in the context of Neurofibromatosis type 1 (NF1), a tumor predisposition syndrome affecting one in 3,000 live births caused by mutations in the NF1 gene." (PMID 38799507, 2024). "The tumor arises in approximately 15 to 30% of children with NF1, a tumor predisposition syndrome caused by the germline mutation in NF1 gene." (PMID 37959175, 2023). "The most common tumor predisposition syndrome is neurofibromatosis type 1 (NF1), which is the consequence of a germline mutation of NF1, a tumor-suppressor gene located on chromosome 17." (PMID 34572171, 2021). "Patients with NF1 often have a high burden of genetic disorder owing to improved tumor predisposition syndrome and limited management options." (PMID 34526571, 2021). "NF-1: neurofibromatosis type 1 (NF-1) is a well-known inherited tumor predisposition syndrome caused by a germline mutation in the NF-1 tumor suppressor gene." (PMID 33673070, 2021). "NF1 is the most common tumor predisposition syndrome in which the loss of tumor suppressor neurofibromin leads to the activation of the Ras proto-oncogene and the development of dozens of benign and malignant tumors." (PMID 32650362, 2020). "This study reveals an impact of the tumor predisposition syndrome NF1 on essential parameters of dental health." (PMID 29670726, 2018). "Neurofibromatosis type 1 (NF1: Online Mendelian Inheritance in Man (OMIM) #162200) is an autosomal dominantly inherited tumour predisposition syndrome." (PMID 28637487, 2017). "The identification of high frequency of somatic NF1 mutations in sporadic tumours indicates that neurofibromin is likely to play a critical role in development, far beyond that evident in the tumour predisposition syndrome NF1." (PMID 28637487, 2017). "Further investigations on additional tumor specimens from more NF1 patients will improve our understanding of the mechanisms of pathogenesis in this tumor predisposition syndrome." (PMID 26432421, 2015). "Neurofibromatosis type 1 (NF1) is a relatively common tumour predisposition syndrome related to germline aberrations of NF1, a tumour suppressor gene." (PMID 25026295, 2014). "Germline mutations of the NF1 gene cause the tumour predisposition syndrome, neurofibromatosis type 1 (NF1), which affects 1/3,000–4,000 individuals worldwide." (PMID 23947441, 2013). "Neurofibromatosis type 1 (NF1), which is caused by heterozygous inactivating pathogenic variants in the NF1, has poor phenotypic expressivity in the early years of life and there are numerous conditions, including many other tumor predisposition syndromes, that can mimic its appearance." (PMID 34325699, 2021). "To define alterations early in tumor formation, we studied nerve tumors in neurofibromatosis 1 (NF1), a tumor predisposition syndrome." (PMID 36134665, 2022). "Neurofibromatosis 1 (NF1) is an inherited, autosomal-dominant, tumor predisposition syndrome with a birth incidence as high as 1:2000." (PMID 34011343, 2021). "Neurofibromatosis type 1 (NF1), the most common tumor predisposition syndrome, occurs when NF1 gene variants result in loss of neurofibromin, a negative regulator of RAS activity." (PMID 37328781, 2023).
juvenile myelomonocytic leukemia (31 papers, 2007 to 2025). A myelodysplastic/myeloproliferative neoplasm of childhood that is characterized by proliferation principally of the granulocytic and monocytic lineages. "Juvenile myelomonocytic leukemia (JMML) is a rare pediatric MDS/MPN overlap syndrome that is characterized by somatic mutations in NF1, CBL, NRAS, KRAS or PTPN11 that result in the activation of RAS/MAPK or JAK/STAT signaling." (PMID 31171568, 2019). "Children with NF1 have a 200–500 fold risk of developing juvenile myelomonocytic leukemia (JMML), an aggressive myeloproliferative disorder (MPD)." (PMID 24386979, 2014). "Juvenile myelomonocytic leukemia (JMML) is a rare and aggressive childhood cancer associated with mutations in the RAS/MAPK signaling pathway, including NF1 mutations, found in 22% of cases according to a recent study using a 51gene myeloid panel." (PMID 41440192, 2025). "Inherited BMFS may predispose to MDS and AML, whereas RASopathies such as NF1 and Noonan/Noonan-like syndromes may predispose to juvenile myelomonocytic leukemia (JMML)." (PMID 38473358, 2024). "Somatic deletion of Nf1 induces a myeloproliferative disorder in mice that models juvenile myelomonocytic leukemia (JMML)." (PMID 34944812, 2021). "Juvenile myelomonocytic leukemia (JMML) is a rare clonal hematopoietic disorder of childhood characterized by monocytosis and loss of function of neurofibromatosis 1 (NF1) or somatic mutations of genes in RAS/MAPK pathway." (PMID 27600067, 2015). "UPD has also been identified as the cause for the cryptic chromosomal aberration for the inactivation of the NF1 gene, a tumor suppressor gene, in juvenile myelomonocytic leukemia." (PMID 19662193, 2007). "A rare manifestation in children with NF1 is the development of juvenile myelomonocytic leukemia (JMML), which can be mimicked in mice by deletion of Nf1 in hematopoietic cells." (PMID 40075752, 2025). "Patients with NF1 and JXG were previously reported as being at risk of developing juvenile myelomonocytic leukemia (JMML)." (PMID 36831560, 2023). "An association between NF1, multiple JXG and juvenile myelomonocytic leukemia (JMML) has been reported in few studies; however, JMML is extremely rare and this association remains controversial." (PMID 32014052, 2020). "Phenotypically related to pCMML, juvenile myelomonocytic leukemia (JMML) is a pediatric neoplasm often initiated by germline (CBL, NF1, PTPN11) or somatic (NRAS, KRAS, CBL, RRAS) RAS-activating mutations and is described as a bona fide RASopathy26,27." (PMID 34006870, 2021). "Deletion of NF1 was particularly interesting since it led us to suspect an alteration of the RAS pathway and a similarity with juvenile myelomonocytic leukemia (JMML)." (PMID 18925961, 2008).
scoliosis (30 papers, 2010 to 2026). A congenital or acquired spinal deformity characterized by lateral curvature of the spine. "Due to the significant differences in treatment and prognosis between the two types of scoliosis associated with NF-1, it is vital to make timely diagnosis on the types of scoliosis." (PMID 41170329, 2025). "Although scoliosis is the most common type of skeletal changes in NF-1, there is limited research on the correlation between specific mutation types and mutation sites in NF-1 patients with scoliosis." (PMID 41170329, 2025). "The presence of scoliosis (29.4%, 5/17) in this group also warrants further investigation given the known association between skeletal abnormalities and NF1." (PMID 39857730, 2025). "The first study, focusing exclusively on a cohort with NF1-associated scoliosis, reported similar correction rates and T1-S1 growth with other studies on the use of growing rods for early-onset scoliosis." (PMID 41517354, 2025). "Dystrophic features and a tendency for rapid progression make NF1-associated scoliosis a significant surgical challenge." (PMID 41517354, 2025). "Considering the inclusion criteria, which cover only NF1-associated scoliosis, most of the studies reviewed include relatively small sample sizes, which limits both comparability and the predictive value of the findings." (PMID 41517354, 2025). "Several studies have shown by genotypic analysis a localized loss of heterozygosity of the NF1 gene in pseudarthrosis or scoliosis tissues, suggesting that biallelic inactivation is necessary to develop bone abnormalities." (PMID 38481529, 2024). "The co-occurrence of scoliosis and spinal tumors was observed in 45% of cases by Koczkowska in patients harboring missense mutations affecting NF1 codons 844-848." (PMID 36612057, 2022). "Finally, only a few studies have assessed the use of magnetically controlled growing rods (MCGR) for the treatment of NF1-associated scoliosis." (PMID 41517354, 2025). "It is generally accepted that scoliosis caused by NF-1 is relatively stiff and the preoperative traction may contribute to the improvement of orthopedic effect." (PMID 32041574, 2020). "Although no clear genotype–phenotype correlation has been established in patients with NF1-associated scoliosis, additional studies regarding this may facilitate the development of personalised and widely accepted surgical management strategies for this rare disease." (PMID 41517354, 2025). "Case 4a 15-year-old female NF1 patient, treated since she was seven years old with posterior growth guidance for a syndromic, dystrophic scoliosis." (PMID 41551866, 2026). "We also identified Prss56-Nf1 mutant mice with scoliosis and high kyphosis angle (above 80°) recapitulating NF1 kyphoscoliosis spine deformity from 12 months of age." (PMID 41397954, 2025). "Correspondingly, loss-of-function mutations in the NF-1 gene inhibit the RAS pathway, impair bone development, and lead to skeletal deformities such as scoliosis and pseudarthrosis." (PMID 41170329, 2025). "Counting of scoliosis-related genes indicated that NF1, FBN1, LAMA2 and SPG11 led the top list of genes concerned with scoliosis." (PMID 39502335, 2024). "The pattern of pulmonary dysfunction in patients with NF-1-related scoliosis is similar to that in IS, with more severe pulmonary dysfunction in patients with thoracic scoliosis." (PMID 36967416, 2023). "Patients with dystrophic scoliosis secondary to NF-1 who underwent corrective scoliosis surgery between March 1998 to January 2018 were identified from our scoliosis database." (PMID 35337307, 2022). "Café au lait macules were associated with scoliosis (OR = 3.83 [1.38, 13.68]), ADD (OR = 2.68 [1.27, 5.86]), and family history of NF1 (OR = 2.32 [1.14, 4.72])." (PMID 32814709, 2020). "NF1 is the most common single gene disorder and at least 23% of patients diagnosed with NF1 will show signs of scoliosis in childhood." (PMID 23342962, 2013).
scoliosis (continued). "NF1-related scoliosis accounts for approximately 3% of all scoliosis cases." (PMID 41517354, 2025). "Scoliosis is the most common disease associated with NF-1, and there are two main types: dystrophic and non-dystrophic." (PMID 36967416, 2023). "In addition, within skeletal abnormalities in our cohort, scoliosis was more frequent, while other abnormalities were more rare than previously reported in large-scale cohorts of classical NF1." (PMID 36612057, 2022). "In our cohort of 438 children with NF1, we found a prevalence of scoliosis of 9.8%." (PMID 34356257, 2021). "It is estimated that approximately 2% of all pediatric scoliosis is due to NF1." (PMID 34356257, 2021). "The optimum treatment for scoliosis in NF-1 patients remains controversial." (PMID 30408738, 2018). "He had been diagnosed with NF-1 because of café-au-lait macules and scoliosis." (PMID 30408738, 2018). "3Cre mice suggests that Nf1 heterozygosity in at least of subset of cell lineages together with biallelic Nf1 inactivation in MSCs/osteoblasts play a critical role in the pathogenesis of scoliosis in theses NF1 murine models." (PMID 25786243, 2015). "Neurofibromatosis type 1 (NF-1) may involve the spine as various abnormalities including bony dysplasia, scoliosis, and nerve sheath tumors." (PMID 25852768, 2014). "A mouse model for modeling human NF1 deficiency is currently available, and while it does not spontaneously develop scoliosis it shows impaired long bone healing and response to rhBMP treatment." (PMID 23342962, 2013). "Scoliosis and tibial dysplasia were only evident in "Twin 1", consistent with the low correlation coefficient of 0.17 established in 6 MZ twins, even though scoliosis was previously reported to be a concordant feature in another 3/3 NF1 MZ twins." (PMID 20687928, 2010). "In addition, evaluation of MDCT imaging may provide an opportunity for further research to refine understanding of scoliosis in patients with NF-1." (PMID 25852768, 2014). "The separation of NF-1 associated scoliosis into dystrophic and nondystrophic curves is made with plain radiographs and may suffer from the inability of such imaging to identify early bone changes." (PMID 25852768, 2014). "Combined with the long term of tinnitus, scoliosis, multiple orifices and the result of whole-exome sequencing, we preferred the AVF associated with NF-1 more likely being a congenital disease rather than a secondary one resulted in vessel vulnerability and friability." (PMID 33815242, 2021). "However, scoliosis seems to be more frequent in underage NF1-deleted patients, though not significantly (8/48 vs. 2/39, p value = 0.183)." (PMID 34199217, 2021).
epilepsy (29 papers, 2014 to 2025). A brain disorder characterized by episodes of abnormally increased neuronal discharge resulting in transient episodes of sensory or motor neurological dysfunction, or psychic dysfunction. "Despite growing interest in rare diseases and recent advancements in NF1 research, most reports on NF1-associated epilepsy remain limited to case studies." (PMID 40895107, 2025). "Although somatic variants in the “two-hit” theory cannot be detected in all cases, accumulating evidence has demonstrated its role in NF1-associated epilepsy." (PMID 40895107, 2025). "NF1-associated epilepsy demonstrates diverse seizure semiologies, with focal seizures being the most prevalent phenotype." (PMID 40895107, 2025). "The over-activation of Ras-signaling caused by NF1 gene variants leads to synaptic plasticity and neuronal activity damage, thus participating in the pathogenesis of epilepsy." (PMID 40895107, 2025). "For instance, only 50% of reported NF1-associated epilepsy cases are structural epilepsies resulting from brain abnormalities detectable on neuroimaging and structural NF1-associated lesions on MRI do not always co-localize with epileptiform discharges on EEG." (PMID 38685949, 2024). "Targeted knockout of the NF1 gene is associated with decreased latency to epilepsy and greater seizure severity in mice." (PMID 35832394, 2022). "Specifically, the association between NF1 and an increased lifetime risk of epilepsy has been reported in different epidemiological studies, which estimated a lifetime prevalence of seizures in this condition ranging from 4% to 14%." (PMID 34944956, 2021). "NF1 has also been associated with focal cortical dysplasia and hemimegalencephaly, both potentially related to epilepsy." (PMID 29566708, 2018). "In addition, some studies have shown that NF1 patients with epilepsy have a higher incidence of truncating variants and a lower incidence of missense variants." (PMID 40895107, 2025). "This review comprehensively summarizes current knowledge regarding the pathogenesis, clinical characteristics, diagnostic approaches, and therapeutic strategies for NF1-related epilepsy, aiming to optimize diagnostic accuracy and treatment outcomes for affected individuals." (PMID 40895107, 2025). "Our findings suggest second-hit environmental events such as early-life immune activation may promote epileptogenesis in the Nf1+/− mouse and may be a risk-factor for NF1-associated epilepsy." (PMID 38685949, 2024). "Although this patient’s seizures were clearly focal in origin, it is possible that MAPK activation due to NF1 germline mutation in neuronal cells might contribute to the severity of his epilepsy and predict response to MEK inhibition." (PMID 35648241, 2022). "In addition to the propensity to develop nervous system tumors, patients with NF1 have an increased risk of epilepsy, with 4–9.5% of patients developing seizures vs 1–2% in the general population." (PMID 35648241, 2022). "Moreover, it has been suggested that second-hit environmental events, such as acute immune activation induced by lipopolysaccharide injection early in life, may promote epilepsy in NF1+/ -mice and may be a risk factor for NF1 related epilepsy." (PMID 40895107, 2025). "This underscores an uncertainty around whether an underlying structural lesion is always the true epileptogenic basis of NF1 epilepsy, or whether there are molecular alterations, driven by disease-associated loss-of-function mutations in Nf1, that mediate NF1-associated hyperexcitability." (PMID 38685949, 2024). "NF1-related epilepsy demonstrates substantial clinical heterogeneity and complex pathogenic mechanisms." (PMID 40895107, 2025). "Neurotransmitter release, neuronal differentiation, cortical development, regulation of ion channel function, synapse formation and synaptic activity involved in NF1 proteins are all crucial for the occurrence of epilepsy." (PMID 40895107, 2025).